CD58 (CD58 molecule)
Diseases named in the same sentence as CD58 in open-access papers (continued):
Sharing a sentence is not in itself a finding about the gene and the disease.
colorectal cancer (6 papers, 2015 to 2025). A primary or metastatic malignant neoplasm that affects the colon or rectum. "Prior research has linked activated CD58 with tumor promotion in colorectal cancer and hepatocellular carcinoma through upregulation of the Wnt/β-catenin pathway." (PMID 41438981, 2025). "We also found a decrease in the expression of RP5-1086K13.1 and its proximal transcript CD58 in leiomyomas which in colorectal cancer cells were found to induce the Wnt/β-catenin pathway; this pathway is known to be activated in leiomyomas." (PMID 35641855, 2022). "In contrast, CD58 expression was significantly increased in multiple solid tumors, including gastric cancer, colorectal cancer, and glioblastomas." (PMID 34193136, 2021). "However, elevated CD58 expression in gastric and colorectal cancer cells was clearly detrimental to immune evasion, so they regarded these findings as “an unexpected direction”." (PMID 34193136, 2021). "The CD58 reduction/loss was not linked to tumor stage, grade, and type, thus illustrating that intercellular adhesiveness of colorectal cancer cells in situ was not affected by aberrant cell-surface levels of CD58." (PMID 34193136, 2021).
glioma (6 papers, 2021 to 2025). A benign or malignant brain and spinal cord tumor that arises from glial cells (astrocytes, oligodendrocytes, ependymal cells). "Conversely, CD58 expression is associated with a decrease in CD8+ T cell infiltration in glioma tissues, consistent with our own experimental outcomes." (PMID 41438981, 2025). "The CD58 marker is a lymphocyte adhesion molecule, found to be overexpressed in gliomas associated with normal brain tissue." (PMID 35625673, 2022). "Cluster of Differentiation 58 (CD58), a critical immune regulator, is implicated in tumor immune evasion, yet its role in remodeling the immunosuppressive microenvironment of gliomas and regulating programmed death-ligand 1 (PD-L1) remains unclear." (PMID 41438981, 2025). "have associated CD58 with tumor progression and poor prognosis in glioma patients." (PMID 41438981, 2025). "This study systematically elucidates the molecular mechanisms through which CD58 enhances glioma progression by increasing PD-L1 expression and reshaping the immunosuppressive microenvironment." (PMID 41438981, 2025). "Our research demonstrates that CD58 promotes glioma cell proliferation, invasion, and migration, consistent with previous findings showing elevated CD58 levels correlate with poor prognosis in various tumors." (PMID 41438981, 2025). "In high-grade gliomas, the expression of CD58 was significantly increased, and it showed statistical differences in relation to clinical pathological indicators." (PMID 41438981, 2025). "CD58 drives glioma progression by upregulating PD-L1 and reshaping the tumor microenvironment toward immunosuppression." (PMID 41438981, 2025). "Our analysis revealed a significant disparity between CD58 expression and T cell infiltration in gliomas." (PMID 41438981, 2025). "In this investigation, we demonstrated a significant reduction in PD-L1 protein levels in glioma upon CD58 down-regulation, as evidenced by functional enrichment analysis and Western blotting." (PMID 41438981, 2025). "Through the integration of multi-omics data from TCGA and CGGA, along with functional validation in glioma cell lines U87MG and LN229, we systematically explored the mechanism underlying CD58’s function in glioma." (PMID 41438981, 2025). "Targeting the CD58-PD-L1 axis presents a novel approach to overcoming the challenges in glioma immunotherapy." (PMID 41438981, 2025). "In vitro experiments demonstrated that knockdown of CD58 in glioma cells significantly inhibited proliferation, migration, and invasion, while enhancing the adhesion of T cells to glioma cells." (PMID 41438981, 2025). "Our integrated analysis nominates CD58 as a potential independent prognostic biomarker and a crucial modulator of immune evasion in glioma." (PMID 41438981, 2025). "This study aimed to elucidate the clinical and mechanistic significance of CD58 in gliomas." (PMID 41438981, 2025). "Notably, in this investigation, CD58 expression significantly surpassed levels in low-grade gliomas (WHO I-II) in high-grade gliomas (WHO III-IV), particularly in aggressive molecular subtypes like IDH wild-type and 1p19q non-codeletion." (PMID 41438981, 2025). "First, CD58 expression patterns, immunorelevance, prognostic significance, and clinical associations were evaluated using transcriptome data from TCGA (33 cancers, n=10,535) and CGGA (glioma, n=1,018)." (PMID 41438981, 2025). "Notably, heightened CD58 expression in gliomas leads to a notable increase in macrophage infiltration, which exhibit immunosuppressive properties, aiding tumors in evading immune surveillance and immune effector cell attacks." (PMID 41438981, 2025). "This molecule is important for immune response, and CD58+ glioma cells are capable of causing tumor onset in vivo, while a significant decrease in CD58 expression by DGH suggests possible modified immunological responses in gliomas." (PMID 35625673, 2022). "Targeting the CD58-PD-L1 axis may enhance immunotherapy efficacy in gliomas." (PMID 41438981, 2025).
glioma (continued). "This investigation highlights CD58 as a potential crucial target for overcoming resistance in gliomas, with implications for different prognostic groups: individuals exhibiting high CD58 expression may derive early therapeutic benefits from combination therapies involving PD-1 inhibitors." (PMID 41438981, 2025). "The notable association of CD58 with IDH wild-type and 1p19q non-co-deletion gliomas implies a relatively “cold” immune microenvironment in IDH mutant gliomas characterized by low T cell infiltration." (PMID 41438981, 2025). "In vitro, CD58 was knocked down in U87MG and LN229 glioma cells." (PMID 41438981, 2025). "However, the reciprocal regulation between CD58 and PD-L1, and its functional implications in glioma immune modulation, have not been investigated." (PMID 41438981, 2025).
acute myeloid leukemia (5 papers, 2021 to 2025). Acute myeloid leukemia (AML) is a group of neoplasms arising from precursor cells committed to the myeloid cell-line differentiation. "Our previous publication demonstrated that low CD58 expression is associated with poor clinical outcomes for cytogenetically normal acute myeloid leukemia (AML) patients." (PMID 35983088, 2022). "To investigate the roles of CMTM6 and CD58 in the antitumor T cell response in vivo, we used an in vivo xenograft model with acute myeloid leukemia (AML) cells treated with CAR-T cells." (PMID 37683639, 2023). "After exposure to GM-CSF, CD58 expression is significantly upregulated in acute myelogenous leukemia (AML) cells." (PMID 34168659, 2021). "In addition to the solid tumor-derived cell models, we also observed reduced CD58 expression upon CMTM6 knockout in B cell lymphoma cells (BJAB and Ramos) and acute myeloid leukemia cells (OCI-AML2)." (PMID 37683639, 2023). "CD58 expression is found on many hematopoietic and nonhematopoietic cells, as well as malignant neoplasms, including CLL, Hodgkin’s lymphoma, multiple myeloma, and acute myeloid leukemias." (PMID 36611312, 2022).
gastric cancer (5 papers, 2021 to 2025). A primary or metastatic malignant neoplasm involving the stomach. "In gastric cancer, elevated expression of CD58 was associated with deteriorated tumor cell invasion, reduced survival time, and cancer recurrence." (PMID 34423049, 2021). "In gastric cancer (GC), high levels of CD58 are associated with cell dedifferentiation, invasion of tumor cells into lymph and blood vessels, decreased survival time, and cancer recurrence." (PMID 34168659, 2021). "We further uncover the molecular mechanism by which HSPA4/ALKBH5/CD58 axis upregulates PDL1 expression in gastric cancer cells and inhibits the cytotoxicity of CD8+ T cells in tumor environment." (PMID 38589927, 2024). "Here we show a different mechanism in gastric cancer: CD58 is negatively posttranscriptionally regulated by HSPA4/ALKBH5 via m6A demethylation." (PMID 38589927, 2024). "A high level of CD58 was related to cellular dedifferentiation and dissemination in gastric cancer, while we found that CD58 was relevant in histological grade and tumor size in PDAC." (PMID 34193136, 2021).
hepatocellular carcinoma (5 papers, 2017 to 2025). A malignant tumor that arises from hepatocytes. "Consequently, CD58 and sCD58 have the potential to serve as significant prognostic indicators for hepatocellular carcinoma, offering new avenues for exploring innovative approaches to treating this form of cancer." (PMID 39156976, 2024). "The expression of CD58 on the surface of hepatocellular carcinoma (HCC) cells is dramatically elevated after anisomycin treatment and blockade of CD58 can potently impair the anisomycin-mediated enhancement of NK cytotoxicity." (PMID 34168659, 2021).
multiple myeloma (5 papers, 2016 to 2025). "Besides dysfunctional CD8+ T-cells, tumor-associated macrophages (CD68+, CD163+, CD86−) and inactivated DCs (CD58−) are also found co-localized with myeloma cells, participating as well in the orchestration of an immunosuppressive state." (PMID 40227595, 2025).
Autoimmunity (4 papers, 2015 to 2025). The occurrence of an immune reaction against the organism's own cells or tissues. "Because the CD2/CD58 interaction stabilizes the HRS/T synapses, monoclonal anti-CD2 antibodies, already in clinical trials for T-cell lymphomas and autoimmune conditions, may counter rosette formation and prove of some benefit in cHL." (PMID 33327433, 2020).
B cell lymphomas (4 papers, 2016 to 2023). "Furthermore, EZH2 has been linked to decreased CD58 expression in B-cell lymphoma, with high H3K27me3 levels at the CD58 promotor region, and increased CD58 expression upon EZH2 inhibition." (PMID 33260693, 2020). "Patients with B cell lymphomas with CD58 defects showed reduced progression-free survival when treated with axicabtagene ciloleucel CAR-T cell therapy." (PMID 36598945, 2023). "To this end, we made use of the CD20+ RAJI B cell lymphoma line, which expresses CD58, the ligand of CD2." (PMID 27117418, 2016).
Candidemia (4 papers, 2016 to 2022). A form of invasive candidiasis where species of CANDIDA are present in the blood. "Recent genomic studies in patients have revealed new host factors for invasive candidiasis: the significant association between candidemia and the single-nucleotide polymorphisms (SNPs) in CD58, LCE4A, and TAGAP loci has been demonstrated." (PMID 35740125, 2022). "In a subsequent GWAS study, the CD58 polymorphism was also associated with persistent candidemia." (PMID 29371502, 2018). "Three additional polymorphisms in CD58, LCE4A-C1orf68, and T-cell activation GTPase activating protein (TAGAP) loci associated with increased susceptibility to candidemia were identified in a genome-wide association study (GWAS) in the largest candidemia cohort to date." (PMID 29371502, 2018).
diffuse large B-cell lymphoma (4 papers, 2016 to 2025). "Genomic inactivation of CD58 resulted in the loss of expression, which was an adverse prognostic factor for diffuse large B-cell lymphoma." (PMID 34193136, 2021). "High CD58 expression in diffuse large B cell lymphoma correlates positively with increased immune cell presence, while reducing CD8+ T cell depletion." (PMID 41438981, 2025). "CD58 is markedly decreased, even lost, in many hematological malignancies, including diffuse large B-cell lymphoma, Burkitt’s lymphoma, chronic myelogenous leukemia, acute lymphoid leukemia." (PMID 34193136, 2021). "In diffuse large B-cell lymphoma (DLBCL), alterations of B2M and CD58 show significant co-occurrence, acting synergistically on the immune escape mechanisms." (PMID 33918793, 2021). "Heatmap analysis demonstrated widespread correlations between CD58 and these immunomodulators in nearly all cancers, except for CHOL, ESCA, diffuse large B-cell lymphoma (DLBC), and uterine carcinosarcoma (UCS)." (PMID 41438981, 2025).
Hodgkins lymphoma (4 papers, 2017 to 2022). A heterogeneous group of malignant lymphoid neoplasms of B-cell origin characterized histologically by the presence of Hodgkin and Reed-Sternberg (HRS) cells in the vast majority of cases. "CD58 mutations are observed in three Hodgkin’s lymphoma cell lines by whole-exome sequencing." (PMID 34682791, 2021).
colon cancer (3 papers, 2017 to 2023). "In colon cancer cells, CD58 was reported to be a strong surface marker for colorectal tumor-initiating cells and promoted the cells’ self-renewal ability by upregulating the Wnt/β-catenin pathway." (PMID 37573318, 2023). "At day three, “Mock” (untreated) colon cancer cells showed significant downregulation of the genes investigated when compared with normal colon, except for CD58 in the Colo201 colon cancer cell line." (PMID 28622390, 2017). "Significant upregulation of CD58 occurred in 2/8 colon cancer lines when treated with 5-AC." (PMID 28622390, 2017). "In 7/8 tested colon cancer lines, CD58 was downregulated when compared with normal colon." (PMID 28622390, 2017).
glioblastoma (3 papers, 2016 to 2025). The most malignant astrocytic tumor (WHO grade IV). "Next, the effect of CD58 on the expression of related proteins in glioblastoma cells was investigated." (PMID 41438981, 2025). "To investigate the role of these accessory adhesion receptor interactions in target cell recognition, we utilized the HLA-A*02:01+ U87 glioblastoma cell line, which expresses CD58 and ICAM-1." (PMID 36598945, 2023). "In glioblastoma (GBM), the expression of CD58 is positively correlated with chemokines, C-C motif chemokine receptors, and immunosuppressive markers." (PMID 41438981, 2025).
HCMV infection (3 papers, 2018 to 2024). "Recently, CD2 and CD58 were found to be greatly upregulated on the adaptive NK cells and fibroblasts under HCMV infection." (PMID 29904386, 2018). "Upregulation of CD2 on NK cells may be a generic response to HCMV infection since the HCMV UL148 gene product reduces expression of CD58, which restricts co-stimulation through CD2 and reduces HCMV-specific T cell and NK cell activation." (PMID 30857329, 2019).
ovarian carcinoma (3 papers, 2017 to 2021). A malignant neoplasm originating from the surface ovarian epithelium. "Treatment of cancer cells with 5-AC also leads to significant re-expression of B2M, CALR, CD58, PSMB8, and PSMB9 at both the RNA and protein level in the colon and ovarian cancer cell lines." (PMID 28622390, 2017). "We confirm that treatment with DNMT inhibitors upregulates expression of the antigen processing and presentation molecules B2M, CALR, CD58, PSMB8, PSMB9 at the RNA and protein level in a wider range of colon and ovarian cancer cell lines and treatment time points than had been described previously." (PMID 28622390, 2017).
pancreatic cancer (3 papers, 2021 to 2025). "In pancreatic cancer, elevated CD58 levels are linked to unfavorable outcomes, vascular invasion, and metastasis." (PMID 41438981, 2025). "Increased levels of SPA17 and CD58 were previously linked to poor prognostic outcome in breast and pancreatic cancer patients, respectively." (PMID 37533202, 2023). "Subsequently, we investigated the effect of CD58 expression on pancreatic cancer prognosis using bioinformatics databases, including TIMER, OncoLnc, GEPIA, and Kaplan–Meier plotter." (PMID 34193136, 2021). "The KEGG pathway strongly suggested that CD58 is involved in pancreatic cancer progression." (PMID 34193136, 2021). "We also further explored CD58 expression in pancreatic cancer in Oncomine, GEPIA, and SurvExpress." (PMID 34193136, 2021).
adrenal carcinoma (2 papers, 2013 to 2021). A carcinoma involving a adrenal gland. "Here we showed high expression of EpCAM, CD56, CD58 and CD90 by flow cytometry in two pediatric carcinomas (an adrenal carcinoma and a nasopharyngeal carcinoma)." (PMID 23472067, 2013).
anaplastic large cell lymphoma (2 papers, 2025). Anaplastic large cell lymphoma (ALCL) is a rare and aggressive peripheral T-cell non-Hodgkin lymphoma, belonging to the group of CD30-positive lymphoproliferative disorders, which affects lymph nodes and extranodal sites. "Research on systemic and cutaneous Dual Specificity Phosphatase-22 (DUSP-22) rearrangements in Anaplastic Lymphoma Kinase (ALK)-negative Anaplastic Large Cell Lymphoma (ALCL) has demonstrated positive CD58 expression, correlating with immune identification of the tumor and a favorable prognosis." (PMID 40365344, 2025). "Across T/NK cell lymphoma subtypes, CD58 expression is frequently lost, affecting >50% of cases in most PTCL categories, with the highest prevalence in ENKTL (83.3%), followed by PTCL-NOS (63.6%) and anaplastic large cell lymphoma (ALCL) (58%), underscoring its potential role in immune escape." (PMID 41295262, 2025).
autoimmune thyroid disease (2 papers, 2018 to 2025). Inflammatory disease of the thyroid gland due to autoimmune responses leading to lymphocytic infiltration of the gland. "Our study revealed enhanced highly significant increase in CD58 (leucocyte function adhesion-3) in autoimmune thyroid groups compared the control group." (PMID 29706856, 2018). "CD58 could also be used as differentiating marker between autoimmune thyroid diseases and non-immune thyroid diseases." (PMID 29706856, 2018).
Burkitt lymphoma (2 papers, 2021 to 2025). A rare form of malignant mature B-cell non-Hodgkin lymphoma. "In contrast, the expression of CD58 was sensitively increased after incubation with IL-4 in human B-lymphoma cells and Burkitt’s lymphoma cell lines." (PMID 34168659, 2021). "The expression of CD58 is markedly elevated in Burkitt’s Lymphoma (BL) compared to BCP-ALL, and it can be used to aid in the diagnosis when BL is suspected but MYC proto-oncogene (C-MYC) rearrangement is negative and the results of surface Ig assessment are controversial." (PMID 40365344, 2025).
central nervous system lymphoma (2 papers, 2021 to 2024). "Given her continued lack of improvement, MSK-IMPACT was performed on the CSF and resulted in the discovery of MYD88, CD58, HIST1H1C, KMT2D, and LCK mutations suggestive of a lymphoid malignancy like primary central nervous system lymphoma (PCNSL)." (PMID 34729485, 2021).
chronic hepatitis (2 papers, 2021 to 2023). An active inflammatory process affecting the liver for more than six months. "This includes CD58, which has been observed on hepatocytic cell lines and in chronic hepatitis." (PMID 36845728, 2023).
COVID-19 (2 papers, 2023 to 2024). A disease caused by infection with severe acute respiratory syndrome coronavirus 2. "This may explain why we found CD58 lowers the risk of severe COVID-19 in our MR study." (PMID 38575325, 2024). "Moreover, we identified several other inflammation-related proteins that are linked to COVID-19, such as CD209, CD58, CCL15, CCL28, and MNDA." (PMID 38575325, 2024). "CD58 is involved in activation of NK and T cells, a reduction in the expression of CD58 results in reduced activation of NK and cytotoxic T cells and may play a role in COVID-19." (PMID 38575325, 2024). "Herein, we spotted CD58, a nonclassical monocyte, such as CD274 (PD-L1) known inhibitor of T-cell activation along with Arginase 1 highly expressed in neutrophils in COVID-19 patients or CD24 involved in neutrophil degranulation with an increased expression of neutrophil function." (PMID 36806094, 2023).
latent infection (2 papers, 2015 to 2021). "We further tested whether prestimulation of resting CD4 T cells with the soluble CD2 ligand CD58 (LFA-3) can also block HIV-1 latent infection of resting CD4 T cells." (PMID 34765923, 2021).